YWHAH (tyrosine 3-monooxygenase/tryptophan 5-monooxygenase activation protein eta)
Diseases named in the same sentence as YWHAH in open-access papers:
YWHAH is named in the same sentence as 47 diseases in open-access papers, as found by Europe PMC text mining. Sharing a sentence is not in itself a finding about the gene and the disease. The quoted sentences say what the papers report.
schizophrenia (8 papers, 2007 to 2022). A major psychotic disorder characterized by abnormalities in the perception or expression of reality. "The proximity of 22q11.2 to the YWHAH gene and the overlapping association with schizophrenia seems to indicate a strong genetic link between 14-3-3η and schizophrenia." (PMID 35359567, 2022). "In further support of this link, both SNPs and variable number tandem repeats (VNTRs) in YWHAH have been associated with schizophrenia in genetic microarray studies." (PMID 35359567, 2022). "Similarly, the down-regulation of YWHAH, a gene linked to schizophrenia that encodes a transcriptional activator of the glucocorticoid receptor and therefore of anti-inflammatory responses, can also be predicted to aggravate neuroinflammation." (PMID 17244347, 2007). "Thus, both YWHAZ and YWHAH genes have been considered as schizophrenia risk genes because they are located chromosomally close to loci that have been genetically associated with schizophrenia." (PMID 35359567, 2022). "YWHAH is related to the pathogenesis of rheumatoid arthritis disease and schizophrenia." (PMID 35902926, 2022). "These PPIs are of particular interest since genetic association studies have previously implicated YWHAE, YWHAH, and YWHAZ with schizophrenia and bipolar disorder and the PBRM1 locus has surpassed genome-wide significance in both schizophrenia and bipolar disorder GWASs." (PMID 27142060, 2016). "Interestingly, five of these genes showed alterations in expression in both ASD and schizophrenia: YWHAB, YWHAE, YWHAH and YWHAZ showed decreased expression whether SFN showed increased expression in both disorders." (PMID 32545830, 2020).
Parkinson disease (6 papers, 2015 to 2023). A progressive degenerative disorder of the central nervous system characterized by loss of dopamine producing neurons in the substantia nigra and the presence of Lewy bodies in the substantia nigra and locus coeruleus. "YWHAH belongs to the 14–3-3 protein family and has been implicated in a variety of neurological disorders including Parkinson and Creutzfeldt-Jakob disease." (PMID 35013429, 2022). "YWHAH were reported to be related to many neurological diseases, including Parkinson’s disease, amyotrophic lateral sclerosis, Alzheimer’s disease, epilepsy, and Creutzfeldt-Jakob disease and is also considered as a candidate gene for neurodegenerative diseases." (PMID 37430323, 2023).
breast carcinoma (4 papers, 2019 to 2024). "To examine the association of KHK-A and S25-phosphorylated YWHAH, we immunologically stained human breast-cancer arrays." (PMID 33116123, 2020). "Collectively, the KHK-A-mediated phosphorylation of YWHAH is likely to be clinically associated with breast-cancer metastasis." (PMID 33116123, 2020). "Next, we investigated whether the KHK-A phosphorylation of YWHAH is clinically associated with breast-cancer metastasis." (PMID 33116123, 2020). "For in vivo evaluation of breast-cancer metastasis, we established the MTV-TM-011 cell lines that stably co-express luciferase and YWHAH or YWHAH_S25A." (PMID 33116123, 2020). "Phosphorylated YWHAH promoted SLUG to repress the CDH1 gene, thereby leading to cell invasion in breast cancer." (PMID 33116123, 2020). "For protein-coding genes, SCUBE2 and SDPR were highly expressed in the luminal A subtype, LAPTM5 and YWHAH in the HER2 subtype, and S100A11 and C6ORF211 in the luminal B subtype of breast cancer." (PMID 31801944, 2019). "Consequently, YWHAH promoted the fructose-dependent invasion of human and murine breast-cancer cells, but the YWHAH_S25A mutant did not." (PMID 33116123, 2020). "Even when the breast-cancer specimens were divided into non-metastasis and metastasis groups, the nuclear KHK-A and S25-phosphorylated YWHAH levels were much higher in the metastasis group." (PMID 33116123, 2020).
gastric cancer (4 papers, 2023 to 2025). A primary or metastatic malignant neoplasm involving the stomach. "Additional evidence from gastric cancer has shown that fructose generated via AKR1B1 activity activates a novel KHK-A/YWHAH/SLUG signaling axis that represses E-cadherin and induces EMT, a key mechanism underlying cancer cell detachment and invasiveness." (PMID 41154825, 2025). "Of the three CDH1 repressors SNAIL, SLUG, and TWIST, YWHAH robustly interacted with SLUG in gastric cancer cells, which was inhibited by silencing AKR1B1 and/or SORD." (PMID 38200154, 2024). "Our results suggested that YWHAH can promote the proliferation of gastric cancer cells by activating the HMGA1/PI3K/AKT/mTOR signaling pathway through Fra-1." (PMID 37415737, 2023). "Specifically, YWHAH has been shown to exert a positive regulatory influence on large B-cell lymphoma and papillary thyroid cancer and to enhance the activity of gastric carcinoma (GC) cells via PI3K/AKT pathway activation." (PMID 38649363, 2024). "To further confirm the effect of silencing YWHAH, we divided gastric cancer cells SGC7901 into three groups: siYWHAH+NC+DMSO, siYWHAH+OE-Fra-1+DMSO, siYWHAH+OE-Fra-1+Rapamycin by transfecting the different plasmids and whether treating cells with rapamycin." (PMID 37415737, 2023). "Above of all, our results suggested that YWHAH could promote the proliferation of gastric cancer cells by activating the PI3K/AKT/mTOR signaling pathway." (PMID 37415737, 2023). "To further confirm that YWHAH promotes gastric cancer cells proliferation by activating the PI3K/AKT/mTOR signaling pathway, we used rapamycin, an inhibitor of the PI3K/AKT/mTOR signaling pathway to treat gastric cancer cells." (PMID 37415737, 2023).
hepatocellular carcinoma (4 papers, 2023 to 2024). A malignant tumor that arises from hepatocytes. "However, YWHAH has also been implicated in hepatocellular carcinoma, where its deletion activates the PI3K/AKT pathway, accelerating epithelial-mesenchymal transition (EMT) and cell cycle progression." (PMID 38649363, 2024). "Conversely, in miR-660-5p-regulated hepatocellular carcinoma (HCC), YWHAH appears to inhibit HCC by suppressing the level of PI3K/AKT phosphorylation." (PMID 38649363, 2024).
thyroid cancer (4 papers, 2022 to 2023). "Additionally, a recent report underlined YWHAH’s role in stimulating thyroid cancer cell proliferation and invasion." (PMID 37529110, 2023). "Specifically, MAPKAPK5-AS1 promotes the proliferation and migration of thyroid cancer cells by targeting miR-519e-5p/YWHAH axis." (PMID 35468721, 2022). "In thyroid cancer, the long noncoding RNA MAPKAPK5-AS1 promoted the proliferation and migration of thyroid cancer cell lines by targeting miR-519e-5p/YWHAH." (PMID 37415737, 2023). "In thyroid cancer, MAPKAPK5-AS1 facilitated cell malignancy by upregulating YWHAH through adsorbing miR-519e-5p, highlighting the oncogenic role of YWHAH." (PMID 35902926, 2022).
epilepsy (3 papers, 2023 to 2025). A brain disorder characterized by episodes of abnormally increased neuronal discharge resulting in transient episodes of sensory or motor neurological dysfunction, or psychic dysfunction. "Our study, through the construction of an SE rat model and in vitro cell model, reveals the significant role and regulatory mechanism of lncRNA‐GPHN in epilepsy pathogenesis via the miR‐320/YWHAH regulatory axis." (PMID 40346986, 2025). "lncRNA‐GPHN ameliorates epilepsy by inhibiting apoptosis via the miR‐320/YWHAH axis, providing insights into epilepsy pathogenesis and potential targeted therapeutic strategies." (PMID 40346986, 2025). "Further validation of lncRNA‐GPHN, miR‐320, and YWHAH expression and function in clinical samples is necessary, especially considering the complex and multifactorial nature of epilepsy." (PMID 40346986, 2025). "To further explore the roles of lncRNA‐GPHN and miR‐320 in epilepsy pathogenesis, we examined their effects on the expression of the apoptosis‐related protein YWHAH." (PMID 40346986, 2025). "Given the crucial role of apoptosis in the pathogenesis of epilepsy, we aimed to explore whether YWHAH is a downstream target regulated by lncRNA‐GPHN/miR‐320." (PMID 40346986, 2025). "The 14‐3‐3 proteins, including YWHAH, influence numerous aspects of brain function, such as neuronal signalling, development, and neuroprotection, with their expression changes potentially impacting neuronal survival and function, thereby contributing to epilepsy pathogenesis." (PMID 40346986, 2025).
deafness (2 papers, 2016 to 2019). An inherited or acquired condition characterized by the complete loss of the ability to hear from one or both ears. "Screening of YWHAH, the gene encoding the 14-3-3eta isoform, in non-syndromic and syndromic deafness, revealed seven non-synonymous variants never reported before." (PMID 27275396, 2016). "Normal morphology and presumably normal fertility in female YWHAH knockout mice have also been recently reported by other investigators who found that absence of YWHAH protein leads to deafness and hair cell degeneration." (PMID 31640562, 2019). "By screening YWHAH gene in non-syndromic and syndromic deafness, we reported seven non-synonymous variations never previously found in this gene." (PMID 27275396, 2016).
glioblastoma (2 papers, 2021 to 2024). The most malignant astrocytic tumor (WHO grade IV). "14-3-3 proteins play important roles in the cell cycle and targeting YWHAH (14-3-3 eta) to enhance mitotic cell death presents a potential therapeutic strategy to overcome radioresistance in glioblastoma." (PMID 34458146, 2021). "The associated ceRNA network revealed the possible presence of the NDUFA6-DT-miR-455-3p-YWHAH/YWHAG axis in low-grade glioma (LGG) and glioblastoma multiforme (GBM), regulating the PI3K-AKT signaling pathway and influencing glioma cell survival and apoptosis." (PMID 38674418, 2024).
glioma (2 papers, 2015 to 2024). A benign or malignant brain and spinal cord tumor that arises from glial cells (astrocytes, oligodendrocytes, ependymal cells). "On a comparison of these two cohorts, we found STUB1 and YWHAH proteins dysregulated in Grade II glioma patients." (PMID 26370624, 2015). "Our enrichment results revealed the participation of YWHAH (14-3-3γ) and YWHAG (14-3-3η) in the PI3K-AKT and Hippo signaling pathways and cell cycle in gliomas." (PMID 38674418, 2024). "In summary, we propose the potential existence of an NDUFA6-DT-miR-3p-YWHAH/YWHAG axis regulating the PI3K-AKT signaling pathway and thereby influencing glioma development in LGG and GBM." (PMID 38674418, 2024). "Specifically, the NDUFA6-DT-miR-455-3p-YWHAH/YWHAG axis may regulate the PI3K-Akt signaling pathway, influencing glioma development." (PMID 38674418, 2024).
Cognitive impairment (1 paper, 2025). Abnormal cognition is characterized by deficits in thinking, reasoning, or remembering. "Combining the previous research results, we conclude that lncRNA‐GPHN negatively regulates miR‐320 to promote YWHAH expression, reducing neuronal apoptosis, and ultimately decreasing seizures, alleviating hippocampal damage, and improving cognitive impairments." (PMID 40346986, 2025).
COVID-19 (1 paper, 2024). A disease caused by infection with severe acute respiratory syndrome coronavirus 2. "In the COVID-19 comparison group, five DEPs, PPP1CA, YWHAH, YWHAB, YWHAZ, and TP53BP2, were enriched with the first three upregulated and TP53BP2 downregulated, whereas the PQ group exhibited enrichment only in Smad4 within this pathway." (PMID 39301288, 2024).
familial partial epilepsy (1 paper, 2019). An instance of partial epilepsy that is caused by an inherited modification of the individual's genome. "YWHAx genes, including YWHAH, have been hypothesized to be involved in neurological disorders including familial partial epilepsy." (PMID 31653223, 2019).
fluorosis (1 paper, 2023). "The top 10 drugs have been reported in previous studies, namely Celastrol, LDN-193189, XPNPEP1, GNB5, Importazole, LDHB, NUAK1, IFNG, IFNB1, and YWHAH, suggesting that these drugs may be effective candidate drugs for the treatment of fluorosis." (PMID 36835629, 2023).
Hyperglycemia (1 paper, 2024). An increased concentration of glucose in the blood. "More importantly, hyperglycemia-induced phosphorylation of YWHAH was almost completely attenuated by silencing AKR1B1 and/or SORD, strongly suggesting that polyol pathway-derived fructose drives S25 phosphorylation of YWHAH." (PMID 38200154, 2024). "Hyperglycemia-induced CDH1 repression was rescued by YWHAH knockdown, and wild-type YWHAH, not the S25A mutant, repressed CDH1." (PMID 38200154, 2024).
liver cancer (1 paper, 2019). An epithelial or non-epithelial malignant neoplasm that arises from the liver. "YWHAH has also been implicated in liver cancer depending on regulated c-myc expression, in insulin resistance and mitochondrial function." (PMID 31717414, 2019).
renal cell carcinoma (1 paper, 2024). "Circular RNA EHD2 (CircEHD2) from renal cell carcinoma cell-derived EVs activates CAFs to accelerate the growth of renal cell carcinoma cells via the circEHD2/YWHAH/YAP/SOX9 signaling pathway." (PMID 39759028, 2024).
viral encephalitis (1 paper, 2025). Encephalitis resulting from viral infection. "The most significant SNP on chromosome 15 was located in the YWHAH gene, which has been implicated in viral encephalitis and tumor progression." (PMID 40427243, 2025).
cancer (15 papers, 2006 to 2024). A tumor composed of atypical neoplastic, often pleomorphic cells that invade other tissues. "Tyrosine 3-monooxygenase/tryptophan 5-monooxygenase activation protein eta (YWHAH) is linked to EV-mediated activation of cancer-associated fibroblasts." (PMID 39336161, 2024). "Therefore, Gremlin 1 and its binding protein YWHAH could be good targets for developing diagnostic and therapeutic strategies against human cancers." (PMID 16545136, 2006). "Numerous studies have reported a correlation between elevated YWHAH expression and various cancer types." (PMID 38649363, 2024). "Our results provide new ideas and an experimental basis to clarify the role and possible mechanism of YWHAH in malignant tumors." (PMID 37415737, 2023). "Also, the combination of YWHAH knockdown and microtubule inhibitor was considered as a possible anti-cancer strategy." (PMID 35902926, 2022). "Thus, the data demonstrate that Gremlin 1 functionally interacts with YWHAH protein to act as an oncoprotein for the genesis of human cancers." (PMID 16545136, 2006). "One of the first reports of a non-BMP binding partner for GREM1 in cancer cells was human tyrosine 3-monooxygenase/tryptophan 5-monooxygenase activation protein eta (14-3-3-eta, also called YWHAH." (PMID 37615860, 2023). "Unlike YWHAG‐deficient cancer cells, YWHAE or YWHAH deficiency did not affect EMT induced by DMOG and TGF‐β." (PMID 37759388, 2023). "YWHAH (14-3-3η), a member of the YWHA (or 14-3-3) family, usually functions by interacting with other proteins to mediate cellular functions, including those in cancer." (PMID 37481520, 2023). "Other candidates, such as AP1B1, APOA1, YWHAH and YWHAZ, however, do not appear to be associated with docetaxel resistance in cancer." (PMID 34948097, 2021).
tumor (9 papers, 2008 to 2026). "YWHAH emerged as a key TNF-associated, m6A-regulated gene, with elevated expression in naive/GC B cells, interleukin (IL)-1β+ tumor-associated macrophages, and differentiated epithelial cells." (PMID 41705255, 2026). "In CRC, YWHAH is stabilized and upregulated via N4-acetylcytidine modification, promoting tumor progression." (PMID 41194917, 2025). "GREM1 was found to be overexpressed in an array of common neoplasms of cervix, ovary, lung, stomach, breast and kidney, and to interact with YWHAH protein to exert a pro-carcinogenic effect." (PMID 35883579, 2022). "The pro-apoptotic CD14, TIA1, and ITGB2 were down-regulated in more than 50% of the tumor cultures after treatment with doxorubicin, as was the antiapoptotic YWHAH." (PMID 18959781, 2008). "NAT10-mediated N4-acetylcytidine modification is critical for YWHAH stabilization, highlighting the central role of epitranscriptomic regulation in modulating the tumor microenvironment and immune escape, and identifying YWHAH as a potential immunotherapeutic target in CRC." (PMID 41194917, 2025). "Overall, these findings suggest that YWHAH may act as a potential tumor suppressor, exerting inhibitory effects on NB." (PMID 38649363, 2024). "Tumor growth was faster in the YWHAH-overexpressing groups than the other groups." (PMID 33116123, 2020). "Therefore, our results illustrate that YWHAH and YAP could partially reverse the tumor-promoting effects induced by circEHD2 in RCC." (PMID 37481520, 2023). "YWHAH, or 14-3-3 eta, is a member of the dimeric 14-3-3 family of signal transduction proteins that specifically binds to phosphorylated serine on a variety of signalling molecules, such as Bcl-2, MDMX, and Bax, thereby promoting cell survival and acting antiapoptotic in several tumor cells." (PMID 18959781, 2008).
neurological diseases (4 papers, 2019 to 2025). "YWHAH is closely related to apoptosis and is implicated in the progression of various neurological diseases." (PMID 40346986, 2025). "Therefore, YWHAH as a protein closely related to neurological diseases, its roles in JEV infection should also be worthy of attention." (PMID 37430323, 2023).
neurodegenerative disease (2 papers, 2023). A disorder of the central nervous system characterized by gradual and progressive loss of neural tissue and neurologic function. "Noteworthy, these studies established the idea that the downregulation, imbalance, or dysfunction of YWHAH could be highly associated with subsequent neuronal loss, which eventually contributes to the development of neurodegenerative diseases." (PMID 36980307, 2023). "Importantly, we identified and validated the expression of YWHAH as a potential target for further characterization of its downstream mechanism and a potential biomarker for the early onset of neurodevelopment and neurodegenerative diseases." (PMID 36980307, 2023).
psychiatric diseases (2 papers, 2020 to 2021). "Interestingly, some genes (such as YWHAH and UHMK1) are genes with functional roles in neurodevelopment and other psychiatric diseases." (PMID 32327736, 2021).
YWHAH also shares sentences with these, for which no sentence is quoted: bipolar disorder (2 papers); colorectal cancer (2); depression (2); papillary thyroid cancer (2); Alzheimer disease (1); amyotrophic lateral sclerosis (1); carcinomas of the (1); carcinomas of the lung (1); cerebrovascular diseases (1); colon tumors (1); Creutzfeldt-Jakob disease (1); epileptic seizures (1); Epstein-Barr virus infection (1); glaucoma (1); ischemia (1); low grade glioma (1); metabolic disorders (1); neuroblastoma (1); Obesity (1); pancreatic cancer (1); Parkinson (1); polydactyly (1); sarcoma (1); status epilepticus (1).